TSPO (translocator protein)
Diseases named in the same sentence as TSPO in open-access papers (continued):
Sharing a sentence is not in itself a finding about the gene and the disease.
schizophrenia (continued). "S1PR1 PET will potentially complement for investigating neuro-inflammation in schizophrenia with other currently used ligands, such as Translocator protein (18 kDa) (TSPO) PET." (PMID 35350429, 2022). "Similar to ASD, TSPO overexpression had originally been predicted in schizophrenia based on preclinical models and increased peripheral cytokines in patients, but was not seen by in vivo PET imaging." (PMID 32076115, 2021). "Our current findings imply the existence of a functional link between TSPO and Iba1 in schizophrenia patients." (PMID 34339805, 2021). "We also find that a substantial component of the [11C]PBR28 PET signal is displaced by XBD173 in schizophrenia, indicating specific binding to TSPO." (PMID 33825022, 2021). "Using the maternal immune activation (MIA) animal model of schizophrenia, a decrease in the TSPO levels was reported." (PMID 33433698, 2021). "Our finding that VND is not altered in schizophrenia has implications for the interpretation of TSPO PET studies in schizophrenia." (PMID 33825022, 2021). "A recent review combining several meta-analyses showed that overall patients with schizophrenia have lowered TSPO concentrations compared to healthy individuals." (PMID 33433698, 2021). "Both autopsy examinations of brains and positron emission tomography (PET) using the TSPO marker (18 kDa translocator protein) indicate the excessive activation of microglia, myeloid immune cells of the nervous system, in schizophrenia." (PMID 34501305, 2021). "In the case of schizophrenia, a reduction of TSPO has instead been observed, though the evidence remains scarce and contradictory." (PMID 32839410, 2020). "For example, in a mouse schizophrenia model, TSPO radioligand binding was decreased in the prefrontal cortex, which did not match the concomitant increases in inflammatory cytokine levels." (PMID 32102369, 2020). "Unfortunately, studies have revealed diverging effects regarding TSPO expression in patients with schizophrenia." (PMID 32252470, 2020). "Compared to some other neuropsychiatric disorders, findings of TSPO PET in schizophrenia and related psychotic disorders have been considerably more heterogeneous." (PMID 32425835, 2020). "A recent study compared TSPO PET of schizophrenia patients and controls with combined peripheral and CSF measures of IL1β, IFNγ, IL-10, IL-6 and TNF-α." (PMID 32179746, 2020). "Most studies of TSPO PET in schizophrenia will include patients that have a history of cannabis use if they remain abstinent during their study participation and/or are inpatients with restricted access to illicit substances." (PMID 32425835, 2020). "Studies using the first-generation radiotracer [11C] PK11195 suggested higher TSPO expression in schizophrenia or equivalent binding relative to controls." (PMID 33354652, 2020). "Studies using newer tracers have shown predominantly null results with one study showing reduced TSPO in individuals with schizophrenia-spectrum diagnoses." (PMID 33354652, 2020). "For these reasons, we do not believe that there is sufficient evidence to suggest an increase in TSPO levels in patients with psychosis or schizophrenia." (PMID 30739609, 2019). "There were a total of 12 studies measuring TSPO tracer binding in 190 patients with schizophrenia-spectrum disorders and 200 healthy controls." (PMID 30355368, 2019). "Although TSPO is ubiquitous and expressed across the whole brain, we cannot exclude that microglia activation in schizophrenia is differentially expressed in specific regions within the brain." (PMID 30355368, 2019). "Unfortunately, later studies using larger cohorts and new TSPO radioligands have been unable to replicate these results in patients with early-stage psychosis or schizophrenia when compared with healthy controls." (PMID 31139952, 2019). "Two small studies utilising PK have demonstrated increased TSPO signal in the grey matter, hippocampus and temporal cortex of patients with schizophrenia." (PMID 31139952, 2019).
schizophrenia (continued). "The lack of an increase, or perhaps even the presence of a decrease in TSPO in patients, at first sight appears to contradict results from other research suggesting a pro-inflammatory state in schizophrenia." (PMID 30739609, 2019). "The difference in 18-kDa translocator protein (TSPO) binding between patients with schizophrenia and healthy controls, as quantified by either binding potential (BP) or volume of distribution (VT), was used as the main outcome." (PMID 30355368, 2019). "Positron emission tomography studies with TSPO tracer evaluating microglial activation in schizophrenia patients versus controls." (PMID 29201010, 2017). "Further studies, preferably using more sensitive TSPO tracers, are warranted to ascertain the role of microglia in the pathophysiology of schizophrenia." (PMID 27602389, 2016). "The first study on TSPO in schizophrenia used the radioligand (R)-[11C]PK11195 in ten patients and ten age-matched healthy control subjects." (PMID 28781965, 2015). "Meta-analyses of PET studies have found evidence for altered TSPO in frontal cortex in schizophrenia relative to controls, albeit the direction of group differences may depend on the outcome measure used." (PMID 41282214, 2025). "Furthermore, microglia were shown to be highly active in people with schizophrenia using TSPO, as the upregulation of TSPO correlates with higher mitochondrial activity." (PMID 38425429, 2024). "An elevation of TSPO expression suggests activated microglia and is therefore suggestive for neuroinflammation We previously demonstrated elevation of TSPO expression in the hippocampus of schizophrenia patients during psychosis using PET." (PMID 37016791, 2023). "However, increased AIF1, CD68, and TSPO mRNA was identified in high immune schizophrenia cases, although the number of microglia per se seemed unchanged." (PMID 31168068, 2021). "TSPO PET studies in schizophrenia patients have shown heterogeneous results." (PMID 33410555, 2021). "However, TSPO tracers were reported to be unable to discriminate patients with schizophrenia from healthy controls." (PMID 34063598, 2021). "The XBD173 binds to the translocator protein (18 kDa) with nanomolar affinity and shows negligible affinity to a broad range of neurotransmitter receptors and our finding indicates a large component of PET signal in schizophrenia is therefore specific binding to TSPO." (PMID 33825022, 2021). "The interpretation of TSPO PET results in schizophrenia is therefore confounded by a medication effect of unknown size." (PMID 32425835, 2020). "In contrast, schizophrenia represents a very particular state in terms of TSPO expression." (PMID 32839410, 2020). "In this section, we discuss aspects of TSPO in neurodegenerative diseases (PD, AD, and HD) and psychiatric disorders, such as schizophrenia and autism spectrum disorder (ASD), as TSPO may present venues for diagnosis and therapy." (PMID 32252470, 2020). "Additionally, in almost all types of CNS pathologies, TSPO levels are increased, and in some psychiatric disorders, such as schizophrenia, the TSPO signal in PET is decreased." (PMID 31963507, 2020). "Likewise, reduced prefrontal TSPO levels were found in an infection-mediated neurodevelopmental mouse model, accompanied with increases in inflammatory cytokines and schizophrenia-relevant behavioral abnormalities." (PMID 32425835, 2020). "Regarding the rates of inflammation, several publications have reported increased microglial activation in post-mortem patients with schizophrenia, accompanied by elevated levels of cytokines in circulation, which may suggest the involvement of TSPO." (PMID 32252470, 2020). "More data from clinical studies employing second generation TSPO radioligands are likely yet to come, hopefully resolving the question on whether TSPO levels are lower, or unchanged in patients with psychosis or schizophrenia." (PMID 30739609, 2019).
schizophrenia (continued). "The SVCA method has been used in (R)-[11C]PK11195 studies to compare TSPO binding between healthy control subjects and patients with Alzheimer’s disease, multiple sclerosis, traumatic brain injury, and schizophrenia or studies which examined changes in TSPO expression in normal aging." (PMID 30498919, 2018). "In addition, we review in this paper 11 original publications on translocator protein (TSPO) positron emission tomography (PET) imaging in schizophrenia." (PMID 29201010, 2017). "Studies conducted so far in vivo and in postmortem human brains and in the Poly(I:C) model of schizophrenia reported upregulation of classical markers of microglial activation such as increased binding of radioligands to the TSPO and increased cytokine levels (reviewed in refs 14, 47)." (PMID 28485733, 2017). "However, there are inconsistencies in the TSPO PET findings in schizophrenia." (PMID 37041418, 2023). "Whereas initial studies in schizophrenia using the first generation TSPO radioligand [11C]PK-11195 showed increased binding in patients, this could not be confirmed in ensuing studies using TSPO radioligands with increased sensitivity such as [11C]PBR28 and [18F]FEPPA." (PMID 35701411, 2022). "Brain imaging studies often rely on radioligand-binding to the translocator protein (TSPO) to detect microgliosis and therefore neuroinflammation, and several studies have found increased TSPO binding in high-risk individuals, first episode psychosis and schizophrenia." (PMID 34650030, 2021). "This is possibly because TSPO is upregulated in the pro-inflammatory context in glial cells, while the morphology of microglia with longer processes and more branches observed in schizophrenia are different from those in Alzheimer’s disease and multiple sclerosis." (PMID 34063598, 2021). "They did find a negative association in patients with schizophrenia, suggesting that TSPO may be related to grey matter loss as the disease progresses." (PMID 33173516, 2020). "There is also evidence for reduced levels of binding of TSPO tracers to TSPO (previously known as the peripheral benzodiazepine receptor) on platelets in schizophrenia, with reductions of ~30% reported in some studies, although potentially only in certain sub-types of schizophrenia." (PMID 30355368, 2019). "Interestingly, the results from this study are inconsistent with the hypothesized increase of TSPO by activated glia in early schizophrenia." (PMID 27070405, 2016). "PET studies using ligands for translocator protein (TSPO), a marker of microglial activation, have demonstrated increased neuroinflammatory activity in patients with both ASD and schizophrenia." (PMID 40724876, 2025). "It is notable that TSPO PET studies of similar sample size have led to disease-specific observations (e.g., schizophrenia: N = 12, ASD: N = 11)." (PMID 38615126, 2024). "Moreover, since peripheral systemic inflammation can lead to microglia activation in the brain, in vivo assessment of microglia activity before and after ECT by 18-kDa translocator protein (TSPO) PET can help to further clarify whether ECT treats schizophrenia by reducing neuroinflammation." (PMID 38233774, 2024). "In schizophrenia patients, a substantial component of the [11C]PBR28 signal represents specific binding to TSPO." (PMID 33825022, 2021). "Empirical evidence of abnormal microglial activity in schizophrenia derives from post-mortem neuropathological studies and in vivo positron emission tomography (PET) with a ligand of the 18kDA translocator protein (TSPO)." (PMID 34339805, 2021). "In this study, we have used the TSPO ligand XBD173 to block the TSPO radioligand [11C]-PBR28 and used an occupancy plot to quantify VND in patients with schizophrenia." (PMID 33825022, 2021).
schizophrenia (continued). "While altered TSPO expression on astrocytes may contribute to the differences, the post-mortem findings of unaltered astrocytic but elevated microglial markers, including elevated TSPO binding, are more suggestive of a microglia activity increase in schizophrenia." (PMID 30355368, 2019). "In patients with recent-onset schizophrenia under antipsychotic treatment, most studies indicate the absence of neuroinflammation, as assessed by TSPO evaluation." (PMID 36443303, 2022). "TSPO-PET imaging and PET/MRI of patients with psychotic disorders detected higher numbers of activated myeloid cells in the grey matter and post-mortem brain tissue also revealed an increase in microglia density in schizophrenia patients compared to controls." (PMID 34363013, 2021). "While brain imaging studies have measured translocator protein (TSPO) in an attempt to assess microglial activation in schizophrenia, TSPO is not specific for microglia and cannot ascertain the role of microglia in the neuropathology of schizophrenia." (PMID 32680547, 2020). "Although the findings involving TSPO signal and schizophrenia have been heterogeneous and controversial, no studies have yet examined TSPO signal between CHR subjects that converted to psychosis and those that did not." (PMID 33173516, 2020). "We observed no significant change in the binding of [11C]DPA-713 to TSPO in 12 patients with recent onset of schizophrenia compared with 14 controls." (PMID 27070405, 2016). "Several lines of evidence ranging from post-mortem to in vivo PET studies targeting the translocator protein (TSPO), overexpressed after microglial activation in the inflammatory-phenotype M1, have demonstrated the primary role of microglia in determining neuroinflammation in schizophrenia." (PMID 41009515, 2025). "Similarly, negative correlations were found between the TSPO signal, an index of microglial activation, and total cortical gray matter volumes in individuals with schizophrenia." (PMID 41009515, 2025). "Therefore, we measured multiple microglial markers including TSPO and macrophage marker CD163 mRNA levels to compare the molecular phenotypes of microglia and macrophages between schizophrenia and normal controls as well as between high and low inflammation subgroups." (PMID 35844224, 2022). "Findings in schizophrenia have shown to vary depending on the outcome measure used and this discrepancy in TSPO results could be explained by lower non-displaceable binding (VND) in schizophrenia, which could obscure increases in specific binding." (PMID 33825022, 2021). "In schizophrenia, a positive correlation between TSPO levels and negative symptoms has been reported and may suggest functional links between the presence of inflammation and the onset of negative symptoms." (PMID 32839410, 2020). "Consequently, the final word regarding neuroinflammation and TSPO in relation to schizophrenia has not been said yet." (PMID 32252470, 2020). "By demonstrating lack of significant change in binding of [11C]DPA-713 in the brains of patients compared with controls, we support previously noted absent detection of change in TSPO using other second-generation PET-based radiotracers in patients with schizophrenia." (PMID 27070405, 2016). "Our results suggest that increased levels of IL-6 may occur in the absence of changed TSPO PET signal in the brains of medicated patients with recent onset of schizophrenia." (PMID 27070405, 2016). "However, TSPO tracers may bind to a number of sites in the blood, including acute phase and inflammatory plasma proteins, such as α1-acid glycoprotein (AGP) that are known to be elevated in schizophrenia." (PMID 30355368, 2019). "Thus, the discrepant TSPO results could be explained by lower non-displaceable binding in schizophrenia, which could obscure increases in specific binding, accounting for the lack of differences reported in many of the studies, and a small decrease in VT on a pooled analysis." (PMID 33825022, 2021).
schizophrenia (continued). "Normal TSPO was observed in a cohort under antipsychotic medication, whereas decreased TSPO levels were found in non-treated FEP patients or recent-onset schizophrenia." (PMID 36443303, 2022). "Together, these findings suggest that the lack of increased TSPO expression or ligand binding by human PET imaging in first-episode psychosis and recent-onset schizophrenia may not reliably exclude the presence of low-grade neuroinflammatory process." (PMID 28588507, 2017).